TNF (tumor necrosis factor)
Diseases named in the same sentence as TNF in open-access papers (continued):
Sharing a sentence is not in itself a finding about the gene and the disease.
neuroblastoma (continued). "The data from White's lab showed that individual SK-N-AS neuroblastoma cells may oscillate in response to stimulation with doses as low as picomolar TNFα, though this response is apparently probabilistic, with the fraction of responsive cells declining with dose." (PMID 22202812, 2012). "CT exposure downregulates mitochondrial oxygen consumption rate in neuroblastoma SH-SY5Y cells, increases IL-6, SOD1, and TNFα expression, and enhances cell apoptosis." (PMID 41424770, 2025). "The analysis of the secretome induced by TRT revealed that neuroblastoma cells (SK-N-BE) treated with 131I-MIBG produced ROS, interleukin-6 (IL-6), and tumor necrosis factor-α (TNF-α)." (PMID 40725216, 2025). "We found significant differences in the serum levels of IL-1β, IL-6, IL-12p40, IL-12p70, TNF-α, IFN-γ, IL-8 and MCP1 between patients with neuroblastoma and the control group." (PMID 40722593, 2025). "PARP4, stimulated by interferon gamma (IFN-γ) and tumor necrosis factor-alpha (TNF-α), mediates apoptosis in human neuroblastoma cells." (PMID 41460301, 2025). "Treatment of the AD SH-SY5Y (human neuroblastoma cells) cell model with DPEO resulted in decreased intracellular levels of Aβ, GSK-3β, P-Tau, IL-1β, TNF-α, IL-6, COX-2, OFR, and HFR, alongside reduced AchE and BchE activities and increased SOD activity." (PMID 39056736, 2024). "In neuroblastoma SH-SY5Y cells, previous studies observed that LPS treatment resulted in the enhanced synthesis of proinflammatory cytokines like TNF-α, IL-1β, and IL-6, while there was a decrease in anti-inflammatory cytokines like IL-10." (PMID 38671881, 2024). "A recent study has shown that the expression of p-AMPK was downregulated in mouse neuroblastoma N2a cells after TNF treatment, suggesting dephosphorylation of AMPK by TNF." (PMID 38598101, 2024). "ROS, inflammatory genes, interleukin (IL) 6, inducible nitric oxide synthase (iNOS), tumor necrosis factor (TNFα), and essential oxidative stress response genes (GCLC, Nqo1, and HO-1) in human neuroblastoma SH-SY5Y cells." (PMID 39036266, 2024). "In line with this, GSEA showed lower activity of inflammatory signaling (inflammatory response, IL-, IFN-, TNFα-, and IL6-JAK-STAT3 signaling) in Ewing sarcoma cDCs than in neuroblastoma cDCs, but higher oxidative phosphorylation." (PMID 37823774, 2023). "In both models, neuroblastoma plasticity can be orientated from a noradrenergic towards a mesenchymal identity in vitro, especially in response to EGF and TNFα factors." (PMID 37142597, 2023). "For example, an early study using transfected neuroblastoma cells compared NF-κB dynamics after a 5 min pulse of TNF-α and after continuous TNF-α stimulation." (PMID 38040923, 2023). "We tested the effect of exposing human neuroblastoma SH-SY5Y cells to IL-1β, TNF-α, and IL-6 on thiamin uptake." (PMID 35750148, 2022). "In the TME, the inflammatory factor tumor necrosis factor α (TNF-α) activates NF-κB, which then enters the nucleus to upregulate the expression of CXCR4, thus promoting metastasis in human neuroblastoma." (PMID 35893797, 2022). "A potential pro-inflammatory effect of PMU on the nervous system cells was assessed measuring the levels of the cytokines TNF-α and IL-1β in the supernatant of PMU-treated cultures of neuroblastoma or microglial cells." (PMID 34281258, 2021). "Transfection of shTHRIL was performed in human neuroblastoma SH-SY5Y cells, followed by the detection of the levels of IL-6, IL-1β, and TNFα." (PMID 33675584, 2021). "Our data showed that TNF-α-upregulated FTMT expression was inhibited by an NF-κB inhibitor, BAY 11-7082, similar to our previous study using IMR-32 neuroblastoma cells." (PMID 32455741, 2020).
neuroblastoma (continued). "Neuroblastoma survivors show signs of immunosenescence early after therapy in CD8+ T cell compartment and elevated plasma TNF-α but in later follow-up immune recovery comes into play." (PMID 32744364, 2020). "Moreover, mangiferin promoted secretion of nerve growth factor (NGF) and tumor necrosis factor (TNF)-α (TNF-α) in human neuroblastoma cells, U138-MG, which suggested that mangiferin increased the level of neurotrophic factors and cytokines and may improve recognition memory." (PMID 31484797, 2019). "Materials and methods included human neuroblastoma cell lines-SK-N-MC, SK-N-SH, and SH-SY5Y, which were treated with IFN-γ and TNF-α individually, or in combination, and were assessed for viability by tetrazolium (MTT) assay." (PMID 29278364, 2017). "In gene expression, data from human neuroblastoma patients, levels of IFN-γ, and TNF-α have strong synergy with Par-4 expression and provide good survival advantage." (PMID 29278364, 2017). "The effect of TNF-α and IFN-γ in regulating Par-4 function led us to investigate if they can be predictors of neuroblastoma in clinical datasets." (PMID 29278364, 2017). "The present study indicates that the inflammatory cytokine, TNF-α, partially functions through the NF-κB signaling pathway to upregulate CXCR4 expression to foster neuroblastoma cell metastasis." (PMID 25503960, 2015). "The inhibitor of NF-κB reduced CXCR4 expression on neuroblastoma cells and resulted in decreased migriation towards SDF-1α in response to TNF-α." (PMID 25503960, 2015). "In the current study, M17 neuroblastoma cultures subjected to OGD demonstrated elevated expression of interleukin and TNF-α during the reperfusion phase." (PMID 24602263, 2014). "We and others have reported that early growth response-1 (Egr-1), an important transcription factor that regulates p35 expression, is rapidly upregulated after NGF or TNF-α treatment in PC12 cells, and after TGF-β1 treatment in B104 rat neuroblastoma cells." (PMID 23668392, 2013). "We observed a marked reduction in MS mRNA within an hour of TNF-α exposure, in SH-SY5Y neuroblastoma cells." (PMID 23437274, 2013). "Our results showed that Rgs10-/- macrophages produced higher levels of pro-inflammatory cytokines including TNF, IL-1β and IL-12p70 in response to LPS treatment and exerted higher cytotoxicity on dopaminergic MN9D neuroblastoma cells." (PMID 24278459, 2013). "To conclude, we investigate ICD signatures following oZIKV infection of paediatric brain tumour cells and propose TNF-alpha as a potential prognostic marker for brain tumour oZIKV therapy, with the only other known prognostic marker being CD24 for neuroblastoma oZIKV therapy." (PMID 40240536, 2025). "Furthermore, it has been shown to exert neuroprotective effects in human neuroblastoma (SHSY5Y), with mitigation of anti-inflammatory markers such as IL-1β and TNF-α and decreased ROS levels." (PMID 40943313, 2025). "The catecholaminergic SH-SY5Y human neuroblastoma cells treated with LIF show increased rates of survival compared to control cells when subjected to the harmful action of peroxides, tumor necrosis factor (TNF), or hypoxic conditions." (PMID 39683685, 2024). "In BV-2 (murine microglial cells) and SH-SY5Y (human neuroblastoma) cells, the use of maple syrup enriched with phenols decreased the levels of ROS, NOS, and inflammatory mediators such as IL-6, prostaglandin E2 (PGE 2), and tumor necrosis factor α (TNF-α)." (PMID 38390994, 2024). "Interestingly, in human neuroblastoma SHSY5Y cells, treatment with different doses of the pro-inflammatory factor TNF-α (1, 5, 10 ng/ml) significantly increased the level of intracellular CARS protein and induced secretion of CARS protein at 24 h." (PMID 38191451, 2024).
neuroblastoma (continued). "Two studies showed that cytokines like tumor necrosis factor alpha (TNFα), Interleukin (IL)-1 and interferon gamma (IFNγ) induce neutrophil adhesion to SK-N-SH and LAN-1 neuroblastoma cell lines by upregulating intercellular adhesion molecule-1 (ICAM-1) expression." (PMID 38087370, 2023). "Human SH-SY5Y neuroblastoma cells, a commonly studied neuronal cell type, were exposed to tumor necrosis factor-alpha (TNF-α) in the presence or absence of glucose." (PMID 36412676, 2022). "Studies on human neuroblastoma cells also showed that the secondary metabolites in the AAE had a more obvious synergistic effect and could inhibit TNF-α mRNA expression after LPS treatment." (PMID 35625074, 2022). "We show that co-treatment, but not individual treatment, of IFN-γ and TNF-α induced cytotoxicity in neuroblastoma cell lines." (PMID 29278364, 2017). "Finally, this study also confirms the invitro finding in clinical datasets, and provides evidence that positive synergy of TNF-α and IFN-γ together with Par-4 is a strong predictor of advance stage neuroblastoma." (PMID 29278364, 2017). "Moreover, we also identified that the majority of patients with positive synergy between TNF-α, IFN-γ, and Par-4 were in stage 4 neuroblastoma with amplified Myc gene expression." (PMID 29278364, 2017). "Upon further close inspection of selected patients with upregulated Par-4 (>0.53-fold changes), TNF-α and IFN-γ levels revealed that most of them were in stage 4 neuroblastomas with amplified myelocytomatosis gene (Myc) that was in line with a previous finding." (PMID 29278364, 2017). "The viability of neuroblastoma was decreased when co-cultured with 50 % supernatant of the YB1 pre-treated macrophages (P < 0.01); however, it could be rescued by TNFα inhibitor (P < 0.01)." (PMID 26286454, 2015). "Additionally, MAGEA9B, along with two other targets of HOXD-AS1 - TNF and CNR1, were recently found to be a part of neuroblastoma signature identified in several datasets." (PMID 25522241, 2014). "This neuroblastoma cell line is known to secrete TNF- α and IL-1β, regardless of differentiation." (PMID 34281258, 2021). "It has been reported that TNF-α itself has the capability to induce reactive oxygen species-dependent inflammasome activation and IL-1β production in neuroblastoma cells, which could support the idea that NLRP3 is secreted out of the cell upon TNF-α-mediated inflammasome activation." (PMID 32271889, 2020). "Nevertheless, this model does not seem to be generally valid for neuroblastoma as we could show that neuroblastoma cells were sensitized by SM LBW242 independent of TNF-α." (PMID 27655666, 2016). "Apoptosis induction in neuroblastoma cell lines using SM BV6 recently has also been demonstrated to be independent of TNF-α signaling Additionally there is evidence that other pathways involving RIP1 could be crucial for SM-mediated sensitization for chemotherapy as well." (PMID 27655666, 2016). "Microglial BV-2 cells, but not neuroblastoma SH-SY5Y cells, released the pro-inflammatory cytokines IL-1β and TNF-α." (PMID 34281258, 2021). "Although all analyzed neuroblastoma cell lines showed differential sensitivity to Smac mimetic LCL161 and regulation of NF-κB, sensitization for VCR-induced apoptosis by LCL161 is probably independent of NF-κB and TNF-α." (PMID 29152118, 2017). "Also, it has been shown to occur during treatment with interferon α in some patients because of production of tumor necrosis factor (TNF) α by mononuclear cells and, secondarily, non-hematologically in various types of carcinoma such as neuroblastoma." (PMID 23057758, 2012).
plaque psoriasis (128 papers, 2006 to 2025). "Inhibition of PDE-4 decreases the expression of pro-inflammatory cytokines implicated in the pathogenesis of plaque psoriasis, such as TNF-⍺, interferon (IFN)-y, IL-2, IL-12, and IL-23." (PMID 40109802, 2025). "NF-κB also functions as both a driver and effector within the TNF-α/IL-23/IL-17 axis, the dominant pathogenic pathway in plaque psoriasis." (PMID 41155329, 2025). "Plaque psoriasis, the most prevalent form, is linked to TNF-α, IL-23, and IL-17 pathways, while pustular psoriasis, a less common type, is associated with IL-36RN genetic mutations." (PMID 40303401, 2025). "Observational studies have shown associations between psoriasis vulgaris and circulating cytokines such as IL-23, IL-17 and TNF-α." (PMID 35769988, 2022). "Thus, we established a simple score scale composed of serum CRP, IL-6 and TNF-α levels to estimate the risk for progressing to PsA among psoriasis vulgaris patients, and validated the scale internally and for a retrospective cohort." (PMID 39335643, 2024). "In this study, the cross-sectional study identified the fact that serum CRP, IL-2, IL-6, TNF-α and IFN-γ levels were significantly increased in PsA patients, and positive serum CRP, IL-6 and TNF-α were independently associated with PsA among psoriasis vulgaris patients." (PMID 39335643, 2024). "It is controversial whether biological drugs for psoriasis vulgaris, e.g., TNF-α inhibitors and IL12/23 inhibitors, reduce the risk for cardiovascular events." (PMID 26910469, 2016). "Infliximab: The TNF-α inhibitor infliximab is used in adults and children over the age of six years with moderate-to-severe plaque psoriasis." (PMID 40109802, 2025). "The most relevant signaling pathways in plaque psoriasis include tumor necrosis factor-alpha (TNF-α), interleukin-23 (IL-23), and interleukin-17 (IL-17)." (PMID 41155814, 2025). "It alleviates inflammation and immune responses by binding to and neutralizing free TNF-α in the body, and it is leveraged for various autoimmune conditions, including PsA and plaque psoriasis." (PMID 40303401, 2025). "As described in the previous section, its anti-inflammatory properties stem from its ability to stabilize an asymmetric conformation of the TNF trimer, and it is under phase 2 investigations for the treatment of RA and plaque psoriasis." (PMID 39297883, 2024). "TNF is an important cytokine in the control and amplification of inflammatory pathways and is already used as a molecular target for the treatment of plaque psoriasis." (PMID 39065604, 2024). "Dose reduction (DR) of first-generation biologics for plaque psoriasis (TNF-alpha inhibitors (i) and interleukin (IL)-12/23i) has been described in a previous scoping review." (PMID 38606178, 2024). "Clinical trials showing guselkumab’s efficacy have been promising, even showing improvement in symptoms of plaque psoriasis patients resistant to adalimumab, a TNF-α inhibitor." (PMID 38292958, 2023). "There is currently a lack of real‐world clinical data regarding the safety and efficacy of coronavirus disease 2019 (COVID‐19) vaccines with respect to plaque psoriasis treatment involving tumor necrosis fact or (TNF)‐α and interleukin (IL‐17A) inhibitors." (PMID 37506146, 2023). "This adverse event is counterintuitive since some tumor necrosis factor inhibitors are indicated for the treatment of plaque psoriasis." (PMID 37369753, 2023). "For patients with moderate to severe plaque psoriasis, biologics that inhibit TNF-α, p40IL-12/23, IL-17, and p19IL-23, as well as an oral phosphodiesterase 4 inhibitor, have emerged as promising therapies." (PMID 37631230, 2023). "Clinical trials have demonstrated that guselkumab is more effective than both placebo and adalimumab, a TNF-a inhibitor, in treating moderate to severe plaque psoriasis." (PMID 38292958, 2023).
plaque psoriasis (continued). "Similar to risankizumab, these common AEs were observed in plaque psoriasis patients assigned to active treatment arms in clinical trials of other IL-23 inhibitors, IL-17A inhibitors, and TNF inhibitors." (PMID 37256136, 2023). "But for moderate to severe plaque psoriasis, therapeutic advancements include biologics such as TNF-α, IL-12/23, IL-17, and IL-23, as well as an oral phosphodiesterase 4 inhibitor." (PMID 37029373, 2023). "The main treatments for moderate to severe plaque psoriasis are biologics, such as anti‐interleukin (IL‐17), anti‐interleukin (IL‐23), and antitumor necrosis factor (TNF‐α), as well as oral agents." (PMID 37506146, 2023). "Certolizumab pegol [CZP], a PEGylated antigen binding fragment of a humanized monoclonal antibody against TNF-alpha, is approved for the treatment of moderate-to-severe plaque psoriasis." (PMID 37809085, 2023). "Inactivated SARS‐CoV‐2 vaccines do not have significant impacts on the safety and efficacy of biologics (TNF‐α inhibitors or IL‐17A inhibitors) in patients with moderate to severe plaque psoriasis." (PMID 37506146, 2023). "In patients with plaque psoriasis who were treated with TNF‐α and IL‐17 A inhibitors, inactivated COVID‐19 vaccines did not alter the original therapeutic advantages of biologics treatment." (PMID 37506146, 2023). "Tumor necrosis factor α (TNF-α) antagonists have been the traditional biological treatment for moderate-to-severe plaque psoriasis." (PMID 35754494, 2022). "Among the investigated biologics, secukinumab was the most used, followed by ustekinumab and TNF inhibitors (17.8%)—mainly adalimumab—a ranking that roughly reflects the prescription patterns for moderate-severe plaque psoriasis in Italy." (PMID 35651996, 2022). "The study showed that suppression of TNF-α-mediated pathways in patients with psoriasis vulgaris and PsA results not only in an increase in fat mass but also in lean mass." (PMID 35330186, 2022). "Physicians often initiate new patients with IL inhibitors instead of TNF inhibitors to treat plaque psoriasis, despite their higher price compared to off-patent TNF inhibitors." (PMID 33953678, 2021). "In particular, certain TNF-α inhibitors were proved to be highly effective and well-tolerated in plaque psoriasis in long-term observation." (PMID 35056961, 2021). "Of the biologic therapies, interleukin (IL) inhibitors were more commonly prescribed in patients with GPP than in those with plaque psoriasis (13.6% vs 0.6%, respectively), as were TNF inhibitors (10.9% vs 0.9%, respectively)." (PMID 34390028, 2021). "The DERMBIO registry of 2161 Danish patients with moderate to severe plaque psoriasis evaluated the safety of ustekinumab (n = 1055), compared to TNF-α inhibitors (adalimumab, etanercept, and infliximab)." (PMID 34884596, 2021). "Patients with GPP were more likely to receive topical steroids (multiple), systemic steroids, tumor necrosis factor inhibitors, and interleukin inhibitors than those with plaque psoriasis." (PMID 34212422, 2021). "The first treatment options for moderate-to-severe plaque psoriasis are the anti-TNF drugs ADA and ETN and the IL-12/23 inhibitor UTK." (PMID 33921427, 2021). "Secukinumab was the most frequently used biologic drug, followed by ustekinumab, tumor necrosis factor (TNF) inhibitors, and ixekizumab, a ranking that roughly corresponds to the prescription trends for moderate-to-severe plaque psoriasis in Italy." (PMID 34488749, 2021). "Another condition that typically aggravates with vaccine-derived abundant expression of IFN-γ and TNF-α is psoriasis vulgaris." (PMID 34698094, 2021). "Certolizumab pegol is a pegylated Fab fragment of a monoclonal antibody targeting TNF-α, indicated in moderate-to-severe plaque psoriasis." (PMID 33916122, 2021). "More relevant yet for the present study, CM-biosynthesized AgNPs have been shown to significantly reduce the release of NO, IL-12, and TNFα from CD68-positive macrophages in human psoriasis plaques." (PMID 35010008, 2021).